ERG (ETS transcription factor ERG)
Diseases named in the same sentence as ERG in open-access papers (continued):
Sharing a sentence is not in itself a finding about the gene and the disease.
prostate carcinoma (continued). "Genomic fusion between the membrane-bound serine protease TMPRSS2 and the ETS-family transcription factor ERG is an early genetic alteration occurring in ~50% of prostate cancers." (PMID 27536883, 2016). "To fully understand the extent of ERG heterogeneity in prostate cancer of young and old patients, we took a “brute force” effort and analyzed all 1592 tumor-containing blocks of 125 prostate cancer patients." (PMID 27530104, 2016). "Although induction of the tumor suppressive miR-200b subfamily by oncogenic ERG appears to be counterintuitive, it is consistent with the observation that the vast majority of primary prostate cancers are slow-growing and indolent." (PMID 27191272, 2016). "We demonstrated that TRIM25 knockdown results in increased ERG stability in TMPRSS2-ERG expressing prostate cancer cells." (PMID 27626314, 2016). "Our previous findings suggest that ERG stability in prostate cancer is modulated by the interplay of ubiquitination and deubiquitination." (PMID 27626314, 2016). "The most common gene rearrangement in prostate cancer is the TMPRSS2-ERG fusion, which results in aberrant expression of the transcription factor ERG." (PMID 27285981, 2016). "In summary, these data show, that homogeneous ERG positivity is very rare in prostate cancer, especially in elderly patients." (PMID 27530104, 2016). "In combination with deletion of the Phosphatase and Tensin Homolog (PTEN) or up-regulation of the oncogenic serine/threonine protein kinase Akt, ERG overexpression induces progression to prostate cancer." (PMID 27208692, 2016). "Other genes that have been implicated in prostate cancer include baculoviral IAP repeat containing 5 (BIRC5), also known as survivin and ERG." (PMID 27144529, 2016). "In conclusion, our work provides novel insights in the regulation of ERG protein stability in prostate cancer." (PMID 27626314, 2016). "In comparison to Caucasian patients, ERG expression is much less common in prostate cancers in African American and Asian populations." (PMID 27191272, 2016). "In a search for ERG target genes, we used recently published genomic profiling of human prostate cancer, in which a comprehensive analysis was applied to define miRNA transcriptomes in 113 prostate tumors." (PMID 27191272, 2016). "In this study, we provide definitive evidence that the miR-200b/a/429 subfamily is an ERG target gene in human prostate cancers." (PMID 27191272, 2016). "In prostate cancers, TMPRSS2-ERG fusion caused by chromosomal translocation is present in approximately 50% of samples and manifests over-expression of a functional ERG transcription factor." (PMID 27191272, 2016). "In the present study, we identified TRIM25 as an ubiquitin ligase that targets N-terminally truncated ERG in fusion-positive VCaP cells, and characterized its effects on ERG stability and its expression in prostate cancer." (PMID 27626314, 2016). "Several studies by us and others have demonstrated ERG interfocal heterogeneity in 28–72 % of ERG-positive prostate cancers, and some of these also intrafocal heterogeneity in 4–42 % of ERG-positive tumor foci." (PMID 27530104, 2016). "The most common fusion event (TMPRSS2 exon 1 with ERG exon 4) has been reported as having an incidence between 20%-80% in prostate cancer." (PMID 27144529, 2016). "The concept of distinguishing two clear-cut prostate cancer categories defined by presence or absence of ETS-gene-fusions has recently been challenged by reports suggesting considerable heterogeneity of ERG fusions in prostate cancer." (PMID 27530104, 2016). "Previous data implicate mTOR-S2448 phosphorylation as indicative for good outcome in ERG-fusion prostate cancers." (PMID 27096957, 2016). "This study was designed to determine frequency and extent of ERG fusion heterogeneity in early-onset prostate cancer (EO-PCA, <50 years) and in elderly patients." (PMID 27530104, 2016).
prostate carcinoma (continued). "The TMPRSS2:ERG gene fusion is one of a series of highly promising prostate cancer (PCa) biomarker alternatives to the controversial serum PSA." (PMID 27470540, 2016). "The TMPRSS2-ERG fusion occurs in approximately 50% of prostate cancer (PCa), resulting in expression of the oncogenic ERG in the prostate." (PMID 27191272, 2016). "The authors also demonstrated that miR-200c is a direct target of ERG and is repressed in ERG fusion-positive prostate cancer." (PMID 27208692, 2016). "We found that 79 of 20261 genes showed marked over-expression (outliers) in certain tumor samples, including 3 previously reported prostate cancer genes (ERG, ETV1, and SPINK1)." (PMID 28027300, 2016). "Co-immunoprecipitation assays demonstrated a physical interaction between the AR and ERG proteins in vCaP cells as well as prostate cancer tissues." (PMID 27208692, 2016). "Recent studies showed that ERG overexpression occurs in at least 50% of prostate cancer cases as a result of gene fusion, with a TMPRESS2-ERG rearrangement being the most common form." (PMID 27863438, 2016). "TRIM25 mRNA and protein expression was increased in ERG rearrangement-positive prostate cancer specimens, and we provide evidence that ERG upregulates TRIM25 expression." (PMID 27626314, 2016). "This is based on our finding of homogeneous ERG positivity in 32 % of 59 small prostate cancer foci measuring 3 mm or less in diameter." (PMID 27530104, 2016). "E26 transformation-specific (ETS)-related gene (ERG) expression was increased 30 to 80 times above normal levels in approximately 50% of prostate cancer." (PMID 27863438, 2016). "Our data suggest that attenuation of miR-449a promotes the invasive phenotype of the ERG-positive CaP in part by inducing the expression of SIRT1 in prostate cancer cells." (PMID 26988912, 2016). "While pure “fusion-type” prostate cancer exists in up to 30 % on a tumor focus level, such a finding is an absolute rarity on the patient level, where homogeneous ERG positive cancers were only seen in ten patients (8 %)." (PMID 27530104, 2016). "Although the miR-200 family of miRNAs can also be regulated at post-transcriptional levels, our evidence indicate that ERG can directly bind to miR-200b/a/429 promoter to facilitate its transcription in prostate cancer cells." (PMID 27191272, 2016). "More recently, we had demonstrated, that ERG fusions occur markedly more often in young than in elderly prostate cancer patients." (PMID 27530104, 2016). "ERG is a transcription factor, which becomes expressed as a result of a gene fusion involving the androgen-regulated gene TMPRSS2 and the ERG locus in about 50% of prostate cancers." (PMID 27861151, 2016). "We also show a positive association with the highly prostate cancer-specific gene rearrangement between TMPRSS2 and the ETS transcription factor family member ERG." (PMID 26575822, 2015). "Gene fusions between the TMPRSS2 5’-untranslated region and the ERG oncogene are found in approximately half of prostate cancer cases." (PMID 26571387, 2015). "In summary, the results of our study argue against a tumor-promoting role of SOX9 in prostate cancer, but demonstrate that loss of SOX9 expression characterizes a particularly aggressive subset of ERG positive cancers harboring PTEN deletions." (PMID 26030748, 2015). "Next to ERG fusions, chromosomal deletions represent the most common recurrent genomic alterations in prostate cancer." (PMID 25825985, 2015). "To further investigate changes in the prostate cancer cells after ERG induction, we analyzed the metabolic profile of the cells using high-throughput tandem mass-spectrometry (LC-MS/MS)." (PMID 26310325, 2015). "Here we investigated the role of ERG in prostate cancer and found that overexpression of ERG resulted in expression of a number of neurotransmitter receptors." (PMID 26310325, 2015).
prostate carcinoma (continued). "The strong association of HOXB13 with positive ERG status expression fits well with the known role of androgen receptor activation for development of ERG fusions in prostate cancer." (PMID 25825985, 2015). "S215 phosphorylation has been observed by mass spectrometry of ERG immunoprecipitated from VCAP prostate cancer cells, indicating that this residue is phosphorylated in cells with the TMPRSS2:ERG fusion." (PMID 25885538, 2015). "Experimental data also suggest that the increased transcriptional activity favors the formation of TMPRSS2:ERG, a fusion gene found in about 50% of prostate cancers." (PMID 26421011, 2015). "Here we investigated how ERG changed the function of prostate cancer cells by transducing LNCaP and PC3 cells with ERG, and measuring changes in gene expression and metabolic profiles." (PMID 26310325, 2015). "ERG also increases androgen receptor (AR) binding in mouse prostate, and increases AR transcriptional output in PTEN-deficient prostate cancer patients." (PMID 26310325, 2015). "Earlier studies have provided evidence for distinct molecular subgroups of prostate cancers defined by TMPRSS2:ERG fusions and several genomic deletions." (PMID 26230842, 2015). "Expression of ERG is an early event in prostate cancer tumorigenesis, but alone is insufficient to induce cancer." (PMID 26310325, 2015). "This overexpression of ERG protein in prostate cancer cells may result in a scenario in which the protein may also be released in body fluids, either through a non-classical secretory pathway and/or lysis of cells, providing ERG as a marker associated with the distinct stage of the disease." (PMID 25889691, 2015). "Several studies already demonstrated the importance of knocking down ERG over-expression by siRNA in prostate cancer; one of them has suggested the targeting of TMPRSS2-ERG fusion with siRNA delivered via liposomal nanovectors." (PMID 25933120, 2015). "Earlier studies had provided evidence for distinct molecular subgroups of prostate cancers defined by TMPRSS2:ERG fusions and several genomic deletions." (PMID 25894226, 2015). "Consistent with these, in a tissue reconstitution model, lentiviral overexpression of ERG (or ETV1) in prostate cells collaborates with activation of the PI3K pathway or the androgen receptor (AR) pathway to induce distinct prostate carcinomas." (PMID 25780911, 2015). "Gene fusions involving the androgen-regulated gene TMPRSS2 and ERG occur in about 50% of prostate cancers and result in strong ERG protein overexpression with consequent deregulation of the expression of a large number of genes." (PMID 25825985, 2015). "The discovery of fusion transcripts involving ERG coding sequences and TMPRSS2 promoter sequences has elucidated a role for ERG in the initiation and progression of prostate cancer in a subset of patients." (PMID 25889691, 2015). "A previous mass spectrometry analysis of ERG immunoprecipitated from prostate cancer cells with a TMPRSS2/ERG fusion, identified S215 phosphorylation, indicating that this modification can occur in vivo." (PMID 25885538, 2015). "With the exception of the TMPRSS2:ERG fusion affecting about 50% of prostate cancers, all other individual translocations also occur at very low frequency (<5%)." (PMID 26293672, 2015). "Prostate cancers are characterized by over-expression of the ETS transcription factor ERG as a result of a somatically acquired fusion event to the regulatory region of the TMPRSS2 gene." (PMID 26172920, 2015). "ERG gene assays, which measure the fusion of TMPRSS2 to ERG in prostate cancer tissues, are underway." (PMID 26267226, 2015). "While ERG and SPINK1 appear to identify discrete molecular subtypes of prostate cancer, only high expression of SPINK1 was associated with improved clinical outcome." (PMID 26172920, 2015).
prostate carcinoma (continued). "The detection of ERG protein expression in biopsied tissues from prostate cancer patients using the highly specific ERG MAb 9FY has been valuable for the stratification of prostate cancer." (PMID 25889691, 2015). "While the functional consequences of this remain to be explored, the implication of both AR and ERG oncogenenic signalling axes provides further weight for the importance of the HES transcriptional network in prostate cancer." (PMID 25560400, 2015). "As expected, multiple motifs of transcription factors involved in prostate cancer pathobiology were found, including ERG, AR, and its pioneer factor FOXA1 (Table EV1)." (PMID 26412853, 2015). "ILK and ERG have been shown to cooperatively drive malignant transformation and epithelial-mesenchymal transition in prostate cancer." (PMID 26230842, 2015). "Conversely, some lineage-specific genes are seen to serve as 5′ partners across multiple different 3′ genes; for example, TMPRSS2 and SLC45A3 in prostate cancer have been observed as 5′ partners of ERG, ETV1, ETV4, ETV5, BRAF, and ELK4." (PMID 26684754, 2015). "In 2009, Nilsson and coworkers demonstrated the presence of two known prostate cancer biomarkers, PCA-3 and TMPRSS2:ERG, in exosomes isolated from the urine of prostate cancer patients." (PMID 25695100, 2015). "ERG is normally expressed in hematopoietic and endothelial cells, but is aberrantly expressed in about one-half of prostate cancers due to a chromosomal rearrangement." (PMID 25885538, 2015). "We show that overexpression of these GRPR targets is restricted to prostate carcinomas harbouring ERG and/or ETV1 rearrangements, establishing their potential as therapeutic targets for these particular molecular subsets of the disease." (PMID 26316886, 2015). "The fusion between androgen regulated TMPRSS2 and ERG genes is present in ~50% of prostate cancer patients in Western countries." (PMID 25221645, 2014). "This rearrangement in prostate cancer leads to androgenic induction of ERG expression and the critical outcomes associated with its overexpression in PCa." (PMID 24968068, 2014). "Many groups have analyzed the presence of TMPRSS2:ERG fusion or ERG protein expression in prostate cancer cohorts with variable outcome." (PMID 25243131, 2014). "While it is unarguable that ERG overexpression is involved in oncogenesis of leukemia and prostate cancers, much less is clear as to how ERG signaling mediates drug resistance." (PMID 24504051, 2014). "From our own studies in leukemia cells and previous reports in prostate cancer genes, we selected the ERG-targeted networks to include: WNT signaling, AKT/PI3K signalling, ERK, DNA repair, and DNA chromatin remodeling." (PMID 24504051, 2014). "In contrast, another study indicated ERG can bind to AR and suppress AR expression in prostate cancer VCaP cells." (PMID 24739220, 2014). "This composite ERG gene signatures correlates well with the clinical characteristics of prostate cancer, and is thought to contribute to disease progression in prostate cancer." (PMID 24504051, 2014). "Fusion of the androgen-dependent TMPRSS2 gene to ETS-transcription factor ERG (TMPRSS2:ERG) is one of the most common genetic alterations in prostate cancer occurring in 50%–70% of tumors." (PMID 25243131, 2014). "ERG gene rearrangement is the most abundant genomic aberrations in prostate cancer that accounts for around 50% of clinically localized disease." (PMID 24606912, 2014). "Due to the high incidence of TMPRSS2-ERG fusion in prostate cancer, recent studies have mainly focused on mapping ERG signaling networks in prostate." (PMID 24504051, 2014). "In prostate cancer ERG protooncogene frequently gains hormonal control by seizing gene regulatory elements of TMPRSS2 through genomic fusion events." (PMID 24418414, 2014). "ERG immunohistochemistry is an easy to perform methodology for detecting TMPRSS2:ERG fusion in prostate cancer." (PMID 25243131, 2014).
prostate carcinoma (continued). "Its function in prostate cancer lies in the overexpression of E26 transformation-specific (ETS) transcription factors, such as ETS-related gene (ERG) and ETS translocation variant 1 (ETV1) through gene fusion." (PMID 24877145, 2014). "For example, ERG signaling did not exert repressive effect on AR expression of ERG-negative and moderate ERG expressing prostate cancer cells." (PMID 24739220, 2014). "The promoter of TDRD1 is hypomethylated and TDRD1 becomes overexpressed in ERG overexpressing prostate cancer cells." (PMID 24739220, 2014). "This experimental data provides a direct evidence that ERG is overexpressed in fusion positive prostate cancer cells." (PMID 24739220, 2014). "In needle-biopsies immunohistochemical ERG detection can be used to discriminate prostate cancer from its mimickers, although the additional value to other markers such as p63, basal cell keratin 5, and AMACR is limited." (PMID 25243131, 2014). "With the landmark identification of a recurrent gene fusion event on chromosome 21 between the TMPRSS2 and ERG genes, prostate cancers are now categorized as "fusion-positive" and "fusion-negative"." (PMID 24739220, 2014). "Exposing ERG overexpressing and PTEN-deficient prostate cancer cells to a combined treatment of PARP inhibitor (rucaparib) and radiation induced senescence." (PMID 24739220, 2014). "Recent research in prostate cancer biology has further clarified that ERG is up-regulated in the glands of the peripheral zone as compared to the transitional zone." (PMID 24739220, 2014). "Laboratory findings indicated that CRISP3 is a direct target of ERG and is strongly overexpressed in prostate cancers with the TMPRSS2-ERG fusion gene." (PMID 24739220, 2014). "ERG rearrangement status was shown to be a significant prognostic predictor of prostate cancer-related survival [HR (95% CI): 3.368 (1.261–8.955), P = 0.015] in univariate analysis." (PMID 24516518, 2014). "The results further highlight the potential for the ratio of ERG splice variants in combination with C-MYC expression to be exploited for diagnostic and therapeutic applications against prostate cancer." (PMID 25221645, 2014). "It has been suggested that ERG overexpression facilitates prostate cancer progression by promoting androgen independence through disruption of androgen-receptor signaling." (PMID 24877145, 2014). "It has lately been shown that phosphorylated ERG regulated expression of chemokine (C-X-C motif) receptor 4 (CXCR4) in prostate cancer cells." (PMID 24739220, 2014). "The migratory and invasive potential of prostate cancer cells was noted to be regulated by ERG mediated expression of Metalloproteinase 9 and Plexin A2." (PMID 24739220, 2014). "Rearrangements between the androgen regulated TMPRSS2 gene promoter and the ETS-related ERG gene result in TMPRSS2-ERG fusion transcripts that have been found in approximately half of prostate cancer cases in the Western world." (PMID 24418414, 2014). "Patients with expression of ERG in high-grade prostatic intraepithelial neoplasia are more likely to develop prostate cancer." (PMID 25277175, 2014). "In Summary, in this study we confirmed significant association between CRISP3 expression and prostate cancer progression as well as a strong link between CRISP3 expression and each of ERG expression and PTEN genomic deletions." (PMID 24606912, 2014). "We also observed increased levels of DSB in ERG-induced leukemia cells, as previously reported in prostate cancer cell lines." (PMID 24504051, 2014). "Recurrent gene fusion between the androgen-regulated gene TMPRSS2 and members of the ETS transcription factor family, most commonly ERG, are present in about 50% of prostate cancer cases." (PMID 24505269, 2014). "Inhibition of PARP by Olaparib specifically sensitized ERG-driven prostate cancer xenograft to the alkylating agent, temozolomide." (PMID 24624361, 2014).